SLC6A4 (solute carrier family 6 member 4)
Diseases named in the same sentence as SLC6A4 in open-access papers (continued):
Sharing a sentence is not in itself a finding about the gene and the disease.
Intellectual disability (2 papers, 2010 to 2012). "We analyzed four functional polymorphisms (rs25531, 5-HTTLPR, VNTR, rs3813034) of the SLC6A4 gene and one functional polymorphism (Val66 Met) of the BDNF gene in 98 patients with non-syndromic mental deficiency (NS-MD) and in an ethnically matched control population of 251 individuals." (PMID 20175892, 2010). "The aim of the current paper is to determine whether particular alleles or genotypes of two crucial genes of these systems, the serotonin transporter gene (SLC6A4) and the brain-derived neurotrophic factor gene (BDNF), are associated with mental deficiency (MD)." (PMID 20175892, 2010).
ischemic stroke (2 papers, 2016 to 2022). A stroke disorder caused by obstruction of blood flow to the brain, due to thrombotic (local blood clot formation) or embolic (due to a blood clot or other material traveling from another site) event. "CASP3, PTGS2, JUN, SLC6A4, and HSP90AA1 rank the top five in terms of degree value, indicating that these targets may be the key targets for FIB to treat ischemic strokes." (PMID 36467049, 2022).
polycystic ovary syndrome (2 papers, 2018 to 2022). A disorder that manifests as multiple cysts on the ovaries. "SLC6A4 5HTTLPR polymorphism was revealed to be related to insulin blood levels and insulin secretion during OGTT in patients with polycystic ovary syndrome (PCOS)." (PMID 35837294, 2022).
Tics (2 papers, 2020 to 2021). Repeated, individually recognizable, intermittent movements or movement fragments that are almost always briefly suppressible and are usually associated with awareness of an urge to perform the movement. "The tendency of higher SLC6A4 expression levels in GTS+OCD individuals than GTS-only may explain why selective serotonin reuptake inhibitors (SSRIs) are more effective in the treatment of OCD symptoms than the treatment of tics." (PMID 33445578, 2021).
acral melanoma (1 paper, 2022). "However, the COMT gene mutation showed a significant association in acral melanoma (P = 0.016), and the SLC6A4 gene mutation had a significant association in patients with TNM stage 0 or I (P = 0.008)." (PMID 36405903, 2022).
alcohol addiction (1 paper, 2025). "The power observed for this factor was 99%, and approximately 10% was explained by the polymorphism of the 5HTT (SLC6A4) genotype and alcohol addiction or lack thereof on the Neuroticism trait score variance." (PMID 40422201, 2025). "In addition, there was a statistically significant impact of 5HTT (SLC6A4) genotype interaction and alcohol addiction or lack of it on the Neuroticism scale (F2,207 = 11.22; p < 0.0001; η2 = 0.098)." (PMID 40422201, 2025).
brain injury (1 paper, 2026). Acute and chronic (see also brain INJURIES, CHRONIC) injuries to the brain, including the cerebral hemispheres, CEREBELLUM, and brain STEM. "Neurotransmission-related genes (BDNF, COMT, DRD1–3, DBH, SLC6A4, HTR2A, APOE) influenced motivation, fatigue, cognitive performance, and brain injury recovery." (PMID 41596414, 2026).
breast tumor (1 paper, 2017). "We found that breast tumors overexpressed SLC6A4 transcripts by an average of 2.8 fold compared to normal breast samples." (PMID 28404880, 2017). "We initially determined whether SLC6A4 transcripts are differentially expressed in breast tumors compared to normal breast samples." (PMID 28404880, 2017). "We also determined whether SLC6A4 copy number varied among breast tumor samples and found that the gene is amplified in a fraction of human breast tumors." (PMID 28404880, 2017). "Hence, we attempted to knockout SLC6A4 in breast tumor cell lines using the CRISPR-Cas9 genome-editing tool with the expectation that cells lacking the gene might be viable." (PMID 28404880, 2017). "Our current efforts are centered on conditionally targeting SLC6A4 and the genes encoding TPH1 and each of the 14 5-HT receptors in human breast tumor cell lines to learn whether loss of each gene phenocopies the effect of selective serotonergic antagonists of their encoded molecular targets." (PMID 28404880, 2017). "This latter study is in accord with our unpublished data suggesting that SLC6A4 is essential for the viability or proliferation of the MCF-7 and HCC1954 breast tumor cell lines." (PMID 28404880, 2017).
delirium (1 paper, 2023). A disorder characterized by confusion; inattentiveness; disorientation; illusions; hallucinations; agitation; and in some instances autonomic nervous system overactivity. "Therefore, we speculate that the lncRNA AABR07042999.1 might act as a ceRNA to sponge miRNA and indirectly regulate Tph2, Slc6a4, Dbh, and Th expression in the EMP-induced delirium-like neuropsychiatric disorders." (PMID 36750928, 2023).
dental caries (1 paper, 2025). The decay of a tooth, in which it becomes softened, discolored, and/or porous. "Furthermore, CCND1 also demonstrated a significant association with the progression of dental caries (odds ratio = 1.15564, 95% CI 1.05554-1.26523, p = 0.0018), while SLC6A4, CASP3, NR3C1, and ANXA1 were linked to diseases of the pulp and periapical tissues." (PMID 41023518, 2025).
diarrhoea (1 paper, 2014). "In animal models, SLC6A4 knockout mice had diarrhoea, which was associated with faster colonic motility that resulted in increased excretion of water in stool." (PMID 24392134, 2014).
gastric ulcer (1 paper, 2018). An ulcerated lesion in the mucosal surface of the stomach.
major depressive episode (1 paper, 2021). "Furthermore, as a 5-HT transporter, SLC6A4 is a critical target of the major depressive episode, and this protein may serve as a novel therapeutic target for PTSD." (PMID 34950028, 2021).
Myocardial fibrosis (1 paper, 2024). "A mouse model with Slc6a4 deleted demonstrated increased myocardial fibrosis compared with nondeleted controls, thus suggesting that diminished SLC6A4 expression plays a role in the pathophysiology of cardiac disease." (PMID 39423037, 2024).
non-small cell lung carcinoma (1 paper, 2025). A group of at least three distinct histological types of lung cancer, including non-small cell squamous cell carcinoma, adenocarcinoma, and large cell carcinoma. "For example, in non-small cell lung cancer (NSCLC), 5-HT triggers the c-Myc/SLC6A4 signaling pathway, enhances 5-HT reuptake in A549 lung cancer cells and establishes a positive feedback mechanism that promotes tumor metastasis." (PMID 41154659, 2025).
Pendred syndrome (1 paper, 2024). Pendred syndrome (PDS) is a clinically variable genetic disorder characterized by bilateral sensorineural hearing loss and euthyroid goiter. "Two patients were found to have a pathogenic mutation in the SLC6A4 gene and were diagnosed with Pendred syndrome as the cause of their hearing loss." (PMID 38390978, 2024).
porphyria (1 paper, 2026). Porphyria is a group of diseases in which substances called porphyrins build up, negatively affecting the skin or nervous system. "Workup revealed an SLC6A4 polymorphism and elevated urinary porphyrins, initially prompting Hemin therapy, though genetic testing for porphyria was negative." (PMID 42306637, 2026).
psychosomatic disorders (1 paper, 2025). "This review first outlines how epigenetic dysregulation contributes to psychosomatic disorders through altered expression of genes such as GRM2, TRPA1, SLC6A4, NR3C1, leptin, BDNF, NAT15, HDAC4, PRKCA, RTN1, PRKG1, and HDAC7." (PMID 41439979, 2025).
pulmonary fibrosis (1 paper, 2022). Chronic progressive interstitial lung disorder characterized by the replacement of the lung tissue by connective tissue, leading to progressive dyspnea, respiratory failure, or right heart failure. "However, we have not found that SLC6A4 has been involved in pulmonary fibrosis." (PMID 36507532, 2022).
pulmonary veno-occlusive disease (1 paper, 2022). "Up-regulation of slc6a4 was detected in primary PH and pulmonary veno-occlusive disease, while slc6a4 expression did not change in secondary PH, caused by the various diseases, compared with control patients." (PMID 36288144, 2022).
temporal lobe epilepsy (1 paper, 2021). A localization-related (focal) form of epilepsy characterized by recurrent seizures that arise from foci within the temporal lobe, most commonly from its mesial aspect. "The aim of this study was to evaluate the methylation profile of the BDNF and SLC6A4, two genes importantly involved in neuroplasticity, in patients with temporal lobe epilepsy (TLE) regarding the development or not of psychiatric comorbidities." (PMID 34912196, 2021).
psychiatric disorder (74 papers, 2006 to 2026). A disorder characterized by behavioral and/or psychological abnormalities, often accompanied by physical symptoms. "This gene encodes serotonin transporter protein, which is the target of many antidepressants, and several studies have reported an association between the SLC6A4 gene mutation and psychiatric disorders." (PMID 36405903, 2022). "In several previous studies, associations between methylation of the SLC6A4 gene and psychiatric disorders are reported." (PMID 36503539, 2022). "Many studies have focused on a polymorphism (5-HTTLPR) in the promoter region of the SLC6A4 gene and associations with several psychiatric disorders are reported." (PMID 36503539, 2022). "The presence of polymorphic variants of the SLC6A4 gene encoding serotonin transporter is known to be associated with psychiatric disorders." (PMID 33868590, 2021). "The SLC6A4 gene has been implicated in psychiatric disorder susceptibility and antidepressant response variability." (PMID 33198140, 2020). "The serotonin transporter gene (SLC6A4) is one of the most extensively investigated genes in psychiatry, and has been implicated in a wide range of psychiatric disorders." (PMID 26401310, 2015). "Recently, serotonin transporter gene (SLC6A4) has been associated not only with psychiatric disorders but also with musical aptitude, attending choral singing and creative dance performance." (PMID 23460800, 2013). "In genetic studies of psychiatric disorders in the pre-genome-wide association study (GWAS) era, one of the most commonly studied loci is the serotonin transporter (SLC6A4) promoter polymorphism, a 43-base-pair insertion/deletion polymorphism in the promoter region (5-HTTLPR)." (PMID 34949768, 2022). "We then examined methylation in a shortlist of genes that were previously associated with early life stress and psychiatric disorders as well as placental functioning: Ank3, Avp, Avpr1a, Avpr1b, Bdnf, Cacna1c, Cyp11b1, Cyp11b2, Fkbp5, Hsd11b1, Igf2, Morc1, Nr3c1, Oxt, Oxtr, Pclo, Slc6a4." (PMID 30655507, 2019). "The gene SLC6A4 has frequently been implicated in psychiatric disorders." (PMID 22594806, 2012). "In humans, an important risk factor for the development of some of the most frequent psychiatric disorders is the serotonin transporter (5-HTT) gene (SLC6A4)." (PMID 36710954, 2022). "Previous studies have reported an association between early life stress and altered methylation of the serotonin transporter gene (SLC6A4), a key candidate gene for several psychiatric disorders." (PMID 26401310, 2015). "In genetic studies of psychiatric disorders, one of the most commonly studied locus in the pre-GWAS era, is the serotonin transporter (5-HTT or SLC6A4) promoter polymorphism, a 43-base-pair insertion/deletion polymorphism in the promoter region (5-HTTLPR) with a long (L) and a short (S) allele." (PMID 34949768, 2022). "Given that the dopaminergic and serotonergic pathways are involved in the etiology of psychiatric disease, this study evaluated the genetic association of dopamine D4 receptor (DRD4) and serotonin transporter (SLC6A4) genes with psychiatric symptom susceptibility among HD patients." (PMID 33784353, 2021). "However, a review conducted by Amad and collaborators did not detect a significant association between BPD and typical candidate genes for vulnerability for psychiatric disorders, such as SLC6A4 (serotonin transporter)." (PMID 34829488, 2021). "If these results can be confirmed in a larger sample, methylation of SLC6A4 CpG sites could be used to screen for 5-HT related psychiatric disorders as well as for the assessment of preventive and corrective interventions." (PMID 22745770, 2012). "DNA methylation of genes coding for key regulators of the serotonin system, such as the serotonin transporter (SLC6A4) and the tryptophan hydroxylase 2 gene (TPH2), has been proposed as a possible gene-by-environment mechanism involved in several psychiatric disorders, including MDD." (PMID 38802956, 2024).
tumor (18 papers, 2012 to 2025). "Inhibition of SLC6A4 has also been associated with decreased tumor proliferation in colorectal cancers." (PMID 36247322, 2022). "We found that only five genes (MITF, CCR7, JAK1, ELN, and SLC6A4) functioned as tumor suppressors, whereas the remaining 17 genes functioned as oncogenes." (PMID 36425071, 2022). "By contrast, MITF, CCR7, JAK1, ELN, and SLC6A4 were lowly expressed in tumor tissues." (PMID 36425071, 2022). "Our study revealed that the expression levels of NAV1, EHMT2, SP1, SLC6A4, OPRD1, and CYP3A4 between the normal and tumor were statistically significant." (PMID 38352696, 2024).
cancer (15 papers, 2018 to 2025). A tumor composed of atypical neoplastic, often pleomorphic cells that invade other tissues. "SLC6A4 is a serotonin re-uptake transporter which has been a target for anti-depressant therapies but recently some mutations have been described in cancer cells." (PMID 36247322, 2022). "Although SLC6A4 mutations have been previously linked with various psychological and neurological disorders, recent studies have implicated this gene in cancer." (PMID 36247322, 2022). "Our study, although preliminary, highlights the importance of SLC6A4 mutations in cancers and opens the door for further investigations of the role of this gene in cellular transformation and immortalization." (PMID 36247322, 2022). "Here, we characterize mutations in SLC6A4 that appear in cancer cells." (PMID 36247322, 2022). "Here, we queried the Catalogue of Somatic Mutations in Cancers (COSMIC) to categorize SLC6A4 mutations reported in human cancers." (PMID 36247322, 2022). "Given that SLC6A4 was highly associated with pain regulation and SLC24A3 has positively correlation with SLC6A4, we hypothesized that SLC24A3 was associated with cancer pain in CESC." (PMID 36798148, 2023). "This preliminary analysis highlights the role of SLC6A4 in human cancers." (PMID 36247322, 2022). "TIMER database was used for pan‐cancer analysis of different pain genes (Nav1, EHMT2, SP1, SLC6A4, COMT, OPRM1, OPRD1, CYP2D6, and CYP3A4)." (PMID 38352696, 2024). "Studies of newborns living in disadvantaged neighborhoods found higher global methylation; higher cord blood leukocyte DNAm of a cancer-relevant gene, MEG3; and differential DNAm at the SLC6A4 gene." (PMID 35380065, 2022).
neurological disorders (6 papers, 2010 to 2022). "One of our top hits showing increased methylation for girls included SLC6A4, Solute Carrier Family 6, that is involved in presynaptic reuptake of norepinephrine and has been implicated in several neurological disorders with sex-differences in prevalence." (PMID 26553366, 2015).
gastrointestinal disorders (4 papers, 2014 to 2024). "Several reports have demonstrated that genetic polymorphism in SLC6A4, affecting 5-HTT expression level is associated with susceptibility to functional gastrointestinal disorders." (PMID 25148529, 2014).
bacterial infection (3 papers, 2015 to 2023). "Further, we used SwissTargetPrediction to predict that its main targets are ALOX5, MCL1, and SLC6A4, and find that it can inhibit bacterial biofilm formation and reduce bacterial infection of cells." (PMID 37275170, 2023).
gastrointestinal disease (3 papers, 2018 to 2024). A disease that occurs in the gastrointestinal system, excluding the hepatobiliary system. "The serotonin transporter (SLC6A4) indirectly regulated the formation of extracellular polymeric substances (EPSs) that induce functional gastrointestinal diseases." (PMID 37275170, 2023).
immune disease (1 paper, 2025). "Genetic and epigenetic studies reveal how BDNF, SLC6A4, and immune disease-associated gene variants predispose to both conditions, with early trauma causing enduring molecular damage by DNA methylation." (PMID 40941042, 2025).
SLC6A4 also shares sentences with these, for which no sentence is quoted: colitis (22 papers); Parkinson disease (21); infection (13); Cognitive deficits (9); Dyskinesia (7); Parkinsonism (7); Alzheimer disease (6); Constipation (6); Hepatic steatosis (6); metabolic syndrome (6); panic disorder (6); eating disorder (5); Glucose intolerance (5); psoriasis (5); Chronic constipation (4); Crohn disease (4); metabolic disorder (4); myocardial infarction (4); neurodevelopmental disorder (4); postpartum depression (4); brain disorder (3); Burkitt lymphoma (3); colon carcinoma (3); Gilles de la Tourette Syndrome (3); inflammation (3); neuropathic pain (3); sleep disorder (3); ulcerative colitis (3); viral infection (3); asthma (2).
A further 132 diseases each share a sentence with SLC6A4 in 2 papers or fewer.